TNF (tumor necrosis factor)
Diseases named in the same sentence as TNF in open-access papers (continued):
Sharing a sentence is not in itself a finding about the gene and the disease.
mitral valve disease (2 papers, 2022). "The detected pathways included TGFB-, NOTCH-, FGF-, WNT-, Cadherin- and VEGF signaling pathways associated with EMT, Integrin- and HIF-1 signaling linked to ECM remodeling and NF-κB-, TNF-, osteoclast differentiation, Endothelin- and IL-17 signaling observed in aortic and mitral valve disease." (PMID 35463757, 2022).
monocytopenia (2 papers, 2012 to 2016). "Furthermore, TNF-α inhibitors have also been shown to cause T-cell death and monocytopenia, both of which are also necessary for granuloma formation and further reducing immunity against such infections." (PMID 23304607, 2012).
motor neuron degeneration (2 papers, 2021 to 2026). "For example, in an ALS model, synbiotic intervention not only rectified gut microbiota dysbiosis but also postponed motor neuron degeneration by reducing plasma interleukin - 6 (IL - 6) and tumor necrosis factor - α (TNF - α) levels." (PMID 41601624, 2026). "Further study is needed to clarify the relationship between CSF ATP levels and several inflammatory cytokines such as TNF-α, IL-6, and COX-2 as well as between CSF ATP levels and blood or CSF NfL, which reflect motor neuron degeneration in patients with ALS." (PMID 34193068, 2021).
necrotizing fasciitis (2 papers, 2012 to 2017). "However, preventing rapid tissue damage using a TNF inhibitor in combination with antibiotics might be an option for patients with much more severe diseases such as necrotizing fasciitis, a life-threatening infection involving the skin, soft tissue, and deep fascia." (PMID 28264025, 2017). "In a mouse necrotizing fasciitis model, the streptococcal DNase Sda1 suppressed TLR9-dependent INF-α and TNF-α induction." (PMID 22719247, 2012). "Similarly, in a murine necrotizing fasciitis model, IFN-α and TNF-α levels were significantly decreased in wild type mice infected with GAS expressing Sda1, whereas no such Sda1-dependent effect was seen in a TLR9-deficient background." (PMID 22719247, 2012).
neuro-degenerative diseases (2 papers, 2016 to 2023). "Although a classical proinflammatory cytokine TNF-α has been previously shown to have potent beneficial effects in autoimmune neurodegeneration, reported herein increase in concentration of serum TNF-α in treated patients with MS had likely no protective input." (PMID 27324388, 2016). "For example, in many neuro-degenerative diseases, typically characterized by an elevated inflammation state, the increase in both intra- and extracellular Glu might be induced by high levels of pro-inflammatory cytokines, especially IL-1β and TNF-α." (PMID 37854352, 2023).
Neurogenic bladder (2 papers, 2022 to 2023). A type of bladder dysfunction caused by neurologic damage. "In a previous animal study examining neurogenic bladder, TNF plays a role in bladder mast cell regulation." (PMID 35203430, 2022). "Some case reports have measured inflammatory biomarkers when treating with Lactobacillus rhamnosus GR-1 and Lactobacillus reuteri RC-14, resulting in attenuated expression of TNF-α, IL-6, IL-8, IL-10 and IL-12 (p70) in the neurogenic bladder of SCI patients with UTIs." (PMID 37291666, 2023).
neutrophilic disease (2 papers, 2023 to 2025). "On the other hand, it is known that anti-TNF therapies could induce and/or aggravate neutrophilic diseases, including PG, acting as additive risk factors for the onset of such manifestations in predisposed individuals." (PMID 37324147, 2023).
nodular melanoma (2 papers, 2008 to 2022). "Among primary nodular melanomas, increased tumor thickness was associated with stronger expression of hypoxia markers TNF-α (p = 0.028) and Apaf-1 (p = 0.05), whereas tumor ulceration was associated with stronger expression of hypoxia markers HIF-1α (p = 0.05) and CAIX (p = 0.03)." (PMID 19061491, 2008).
ocular cicatricial pemphigoid (2 papers, 2020 to 2025). Ocular cicatricial pemphigoid (OCP) is a form of mucous membrane pemphigoid (a group of rare, chronic autoimmune disorders) that affects the eyes. "We found positive reactivity of the molecular chaperone BiP/GRP78 in conjunctival epithelium of patients with ocular cicatricial pemphigoid and increased levels of BiP/GRP78, sXBP1 and GRP94 in human corneal epithelial cells treated with TNFα." (PMID 32042069, 2020).
onychomycosis (2 papers, 2021 to 2024). "Three out of four studies, including a randomized prospective study, showed a higher prevalence of onychomycosis in psoriatic patients treated with anti-TNF than in patients that received other types of treatments." (PMID 34938812, 2021).
otitis media with effusion (2 papers, 1995 to 2007). Otitis media associated with accumulation of fluid in the middle ear. "We measured sIL-2R, TNF-α and sICAM-1 in the sera and middle ear effusions (MEEs) of patients with otitis media with effusion (OME)." (PMID 18475663, 1995).
ovarian hyperstimulation syndrome (2 papers, 2020 to 2024). A complication of ovulation induction in infertility treatment. "On the other hand, buffaloes that did not respond to treatment suffered from several pathological conditions of the ovary and uterus, as noted in our histopathological examination.IL-1, IL-6, IL-8, and TNF-α levels were found to be increased in ovarian hyperstimulation syndrome." (PMID 39495423, 2024).
Pachydermoperiostosis (2 papers, 2013 to 2017). with prominent pachydermia and minimal-to-absent skeletal changes. "Here, we report the complicated case of a patient with pachydermoperiostosis combined with spondyloarthritides, who was refractory to steroids and tumor necrosis factor alpha antagonists." (PMID 24330652, 2013). "We report the complicated case of a patient with pachydermoperiostosis and spondyloarthritides who was refractory to steroids and tumor necrosis factor alpha (TNF-α) antagonists, treated by administration of zoledronic acid and an arthroscopic synovectomy with a satisfactory outcome." (PMID 24330652, 2013).
panniculitis (2 papers, 2023). Inflammation of the subcutaneous adipose tissue. "Another evidence that verifies the entity of ERA with panniculitis is the high efficacy of anti-TNF-α therapy." (PMID 37697374, 2023). "Therefore, treating panniculitis with anti-TNF-α agents that are equally effective for ERA is reasonable." (PMID 37697374, 2023).
peanut allergy (2 papers, 2018 to 2021). "For example, it has been shown that LGG is able to reduce the expression of TNFα, IL-17, and RANKL in cells isolated from the small intestine and bone marrow of mice, decreasing bone resorption, and also have desensitizing effects in cow’s milk and peanut allergy." (PMID 35010543, 2021).
pelvic organ prolapse (2 papers, 2024 to 2025). Abnormal descent of a pelvic organ resulting in the protrusion of the organ beyond its normal anatomical confines. "Our findings revealed a significant elevation in interleukin (IL)‐6 and TNF‐α, and matrix metalloproteinase‐2 (MMP2) levels in the vaginal wall tissues of patients with pelvic organ prolapse (POP) compared with the control group." (PMID 38898783, 2024). "To compare the levels of IL‐6, TNF‐α and MMP2 in vaginal wall tissues between patients diagnosed with pelvic organ prolapse and a control group, we gathered a total of 80 vaginal wall tissue samples." (PMID 38898783, 2024).
periapical abscesses (2 papers, 2021 to 2024). "Moreover, the incidence of periapical abscesses in patients treated with Etanercept (a TNF-α inhibitor) was significantly lower than in those treated with methotrexate or salazopyridine, suggesting that TNF-α inhibitors can reduce the incidence of periapical abscesses in RA patients." (PMID 39346909, 2024).
Perthes disease (2 papers, 2023 to 2024). "Previous studies have demonstrated that certain cytokines, including IL-6, IL-1β, and tumor necrosis factor (TNF)-α, are overexpressed in individuals with Perthes disease." (PMID 37303951, 2023).
PFAPA (2 papers, 2022 to 2024). "Studies have shown that S. salivarius K-12 is able to antagonize PFAPA syndrome attacks by elevating salivary gamma-interferon concentrations without modifications in TNF-alpha or IL-1 beta levels and by lowering IL-8 release." (PMID 39768321, 2024).
pituitary apoplexy (2 papers, 2011 to 2018). A rare, potentially life-threatening disorder caused by acute ischemic infarction or hemorrhage in the pituitary gland. "Tumor necrosis factor alpha (TNF-α) is a critical cytokine mediating various hemorrhagic events, but little is known about its involvement in pituitary apoplexy." (PMID 21747731, 2011). "The vascular endothelial growth factor, tumor necrosis factor-α (TNF-α), pituitary tumor-transforming gene (PTTG), matrix metalloproteinase-2/9 (MMP-2/9), proliferating marker (Ki-67), as well as hypoxia-inducing factor are the major contributing factors involved in pituitary apoplexy." (PMID 29615979, 2018).
Pneumocystis infection (2 papers, 2020 to 2024). "In addition, studies of human COPD patients infected with Pneumocystis jirovecii (the causative agent of human Pneumocystis infection) showed that the detection of this fungus correlates with higher pro-inflammatory cytokines levels, such as TNFα, IL6, and IL8." (PMID 38542124, 2024). "The infection occurred with a higher CD4+ count (above 240) than the suspicious level of Pneumocystis infection in HIV patients, which was thought to be due to TNF-α use with HIV infection." (PMID 33209528, 2020). "Use of infliximab in an HIV-positive patient was associated with the occurrence of OI of P. jiroveci infection even with higher CD4+ count (above 240) than the suspicious level of Pneumocystis infection occurrence in HIV patients, which was thought due to TNF-α use with HIV infection." (PMID 33209528, 2020).
polyarteritis nodosa (2 papers, 2017 to 2021). Polyarteritis nodosa (PAN) is a rare, clinically heterogeneous, rheumatologic disease characterized by necrotizing inflammatory lesions affecting small- and medium-sized blood vessels. "An immunohistochemical analysis of a different aneurysm resected from the same patient demonstrated aneurysm wall inflammation with TNFα and NFκB involvement, and the patient was clinically diagnosed with polyarteritis nodosa." (PMID 34887823, 2021). "Future studies will be needed to demonstrate the causation and disease modification with the immunomodulating therapies, such as with the anti-TNFα monoclonal antibody infliximab, that has already shown promise in the treatment of extracranial aneurysms for the patients with polyarteritis nodosa." (PMID 34887823, 2021).
polycystic kidney disease (2 papers, 2012 to 2013). A usually autosomal dominant and less frequently autosomal recessive genetic disorder characterized by the presence of numerous cysts in the kidneys leading to end-stage renal failure. "Interestingly, we found that a number of the nodes had previously been linked to polycystic kidney disease (TNF, AGT, AVP)." (PMID 23209428, 2012). "TNF-α was shown to be a both necessary and sufficient modifier of polycystic kidney disease." (PMID 24160989, 2013).
postherpetic neuralgia (2 papers, 2025). "The results of multi-factor Logistic regression analysis showed that age, CD4+/CD8+ ratio, Treg cell ratio, IL-6, TNF-α, and IL-10 were the independent risk factors for postherpetic neuralgia (p < 0.05)." (PMID 40606470, 2025). "The combined application of TNF inhibitors and antiviral drugs offers potential for both acute pain alleviation and postherpetic neuralgia (PHN) prevention." (PMID 40688076, 2025).
pregnancy-induced hypertension (2 papers, 2021 to 2023). "Levels of inflammatory mediators (IL-6, TNF-α, and hs-CRP) in pregnancy-induced hypertension (PIH) patients have a positive link with the SBP and a poor fetal prognosis of patients, which could be utilized as a parameter of prognosis estimation of PIH patients." (PMID 37759223, 2023).
Primary glaucoma (2 papers, 2022 to 2023). "Aqueous humor levels of other biomarkers are also elevated in canine eyes with primary glaucoma, including TNF-α, matrix metalloproteinases (MMP-2, MMP-9), and transforming growth factor-beta (TGF-β)." (PMID 38200841, 2023). "Further investigation is needed to determine the pathophysiology of increased TNFα and IL-18 in primary glaucoma eyes." (PMID 35998207, 2022). "Primary glaucomatous eyes had the highest levels of IL-18 and TNFα which may indicate that inflammation plays a role in the pathogenesis of primary glaucoma in dogs." (PMID 35998207, 2022).
protein-energy malnutrition (2 papers, 2020 to 2025). A nutritional deficit that is caused by inadequate protein or calorie intake. "Protein-energy malnutrition, even of its subclinical form, is associated with the presence of elevated levels of proinflammatory cytokines such as TNF-α and IL-6, which play central roles in the pathophysiology of both nociceptive and neuropathic pain." (PMID 40917986, 2025). "Increased TNF-α serum levels have been documented in children with protein-energy malnutrition and in the whole blood cultures from children with primary malnutrition, compared to well-nourished ones." (PMID 32401929, 2020).
ptosis (2 papers, 2011 to 2020). The drooping of the upper eyelid. "For instance, IL-1b, IL-6 and TNF-α have well documented sickness effects (e.g. ptosis, piloerection, curled body posture) that are related to hypothalamic neurochemical activity." (PMID 21745392, 2011).
R6 (2 papers, 2020 to 2022). "Hsiao and colleagues showed that inhibition of TNF-α improved motor function, reduced caspase activation, diminished the aggregates, increased neuronal density and decreased gliosis in the brains of R6/2 HD mice." (PMID 33196459, 2020).
Ramsay-Hunt syndrome (2 papers, 2014 to 2024). "In the case presented in this paper, it is assumed that inhibition of TNF-α by IFX promoted the reactivation of latently infected VZV in the geniculate ganglion of facial nerve and caused Ramsay Hunt syndrome." (PMID 24660085, 2014).
renal adenocarcinoma (2 papers, 2021 to 2022). "There is evidence that PrPC contributes to the resistance against tumor necrosis factor α (TNF-α) apoptosis pathway in renal adenocarcinoma." (PMID 34067472, 2021). "PrPC-expressing renal adenocarcinoma cells (ACHN cells) demonstrated a modest but statistically significant increase in cell viability compared with the control group via the suppression of TNF-α-induced cell death, and the PrPC expression in ACHN led to a higher proliferative index." (PMID 34067472, 2021). "PrPC (cellular prion protein), well known for its roles in neurodegenerative diseases, has also been corroborated for the ability to resist tumor necrosis factor α (TNFα) apoptosis in OSCC, colonic, and the renal adenocarcinoma ACHN." (PMID 35563151, 2022).
Renal atrophy (2 papers, 2013 to 2024). Atrophy of the kidney. "TNF-α induces renal tubular apoptosis in patients with renal IRI, resulting in renal atrophy." (PMID 39715172, 2024).
renal tubular acidosis (2 papers, 2023 to 2025). A group of genetic disorders of the kidney tubules characterized by the accumulation of metabolically produced acids with elevated plasma chloride, hyperchloremic metabolic acidosis. "We consider that the activated T cells produce more IL-4, IL-10, IFN-γ and TNF-α during pSS complicated by renal tubular acidosis, leading to the activation of B cells and thus more autoantibodies." (PMID 37391717, 2023).
respiratory allergic diseases (2 papers, 2021 to 2022). "The literature shows that the contractile reactivity of the trachea in respiratory allergic diseases is accompanied by an increase in inflammatory markers such as interleukin-4 and -5 and tumor necrosis factor-α (TNF-α)." (PMID 35712706, 2022).
Respiratory insufficiency (2 papers, 2024 to 2025). "First, transfusion of allogeneic blood products activatessystemic inflammatory responses and releases pro-inflammatory cytokines (e.g.,interleukin 6, tumor necrosis factor-α), leading to pulmonary capillaryleakage and alveolar edema, which in turn exacerbates respiratory insufficiency." (PMID 40630459, 2025). "However, in all three cases of ALS development, the TNF-α inhibitor discontinuation did not induce any symptom improvement, and the disease progress finally led to the patient’s death by respiratory insufficiency." (PMID 39336450, 2024).
Reye syndrome (2 papers, 2020 to 2023). An acute and potentially fatal metabolic disorder characterized by cerebral edema, fatty liver and hypoglycemia. "First, in classical Reye syndrome, proinflammatory cytokines, such as tumor necrosis factor (TNF), mediate the metabolic effects of toxins and drugs causative of this syndrome, indicating that cytokine storm impairs mitochondrial function." (PMID 36761411, 2023).
salpingitis (2 papers, 2019 to 2025). Acute or chronic inflammation of the fallopian tube. "In this study, serum levels of BAFF, TNF-α and IL-6 were all significantly increased in patients with salpingitis and tubal pregnancy in comparison to control group." (PMID 31088412, 2019). "We found statistically significantly elevated expressions of BAFF mRNA or protein in whole tissue samples, and serum levels of BAFF, TNF-α and IL-6 in whole blood samples from patients with salpingitis and tubal pregnancy, in comparison to the control group." (PMID 31088412, 2019). "We found that serum TNF-α and IL-6 were expressed significantly higher in patients with salpingitis and tubal pregnancy, which supported previous studies." (PMID 31088412, 2019). "Serum levels of BAFF, TNF-α and IL-6 were significantly higher in salpingitis group or in tubal pregnancy group when compared to control group (P < 0.01)." (PMID 31088412, 2019). "In this study, the effects of E2 and P4 on the expression of IL-1β, TNF-α, IL-10, and mBD-2 in LPS-stimulated fallopian tube epithelial cells, as well as the potential mediation of postinjury salpingitis through the NF-κB, MAPK, and PI3K/Akt pathways, were investigated." (PMID 40604711, 2025). "Estrogen and progesterone can protect against LPS-induced mouse salpingitis by inhibiting the activation of the NF-κB, MAPK, and PI3K/Akt signaling pathways and suppressing the expression of the inflammatory factors IL-1β, TNF-α, IL-10, and mBD-2." (PMID 40604711, 2025).
secondary hyperparathyroidism (2 papers, 2023 to 2024). Overproduction of parathyroid hormone in response to influence external to the parathyroid glands. "This in turn results in secondary hyperparathyroidism, as well as chronic inflammation causing increased production of pro-inflammatory cytokines in the mucosa and serum, particularly TNFα, IL-1, and IL-6 disrupting bone growth and autoimmune factors." (PMID 38049681, 2024). "Paricalcitol treatment was observed to significantly decrease serum levels of IL-6, TNF, and TGF-βin kidney transplant recipients with secondary hyperparathyroidism or proteinuria." (PMID 37483634, 2023).
short bowel syndrome (2 papers, 2018 to 2020). "Moreover, oral supplementation of LSM to short bowel syndrome rats recovering from intestinal resection, reduced mucosal and systemic inflammation as shown by reduced concentrations of endotoxin in the serum and lowered pro-inflammatory cytokines (IL-6 and TNF-α) in the intestinal tissue." (PMID 30042761, 2018).
skin atrophy (2 papers, 2018 to 2025). The degeneration and thinning of the epidermis and dermis. "Although effective, TCS may cause adverse effects, including increased susceptibility to infections and skin atrophy, and failure to respond to these topical agents can lead to patients being treated with biologics, most commonly an anti-TNF-α inhibitor." (PMID 29593534, 2018).
skin papilloma (2 papers, 2020 to 2022). A benign papillary neoplastic growth on the skin composed of epithelial cells and a fibrous stalk. "Apart from its clear enzymatic role in cholesterol biosynthesis, Tm7sf2 has been shown to be important for liver regeneration, in skin papilloma formation, and affecting nuclear factor kappa B (NF-κB) activity and TNFα expression." (PMID 33330474, 2020).